IL2 (interleukin 2)
Diseases named in the same sentence as IL2 in open-access papers (continued):
Sharing a sentence is not in itself a finding about the gene and the disease.
tumor (continued). "The potent immune effects of interleukin‐2 (IL‐2) for cancer therapy can be increased by genetic fusion of IL‐2 to the Fc domain of an antibody (IL‐2‐Fc) or tumor targeted by genetic fusion to a whole antibody known as an immunocytokine (ICK)." (PMID 38317590, 2024). "As a consequence, due to the binding of the antibody to the antigen on the tumor, the local concentration of IL-2 is increased at the tumor site." (PMID 38337114, 2024). "PD-1-laIL-2 displayed superior tumor inhibition and lower toxicity compared to single or combined treatments of anti-PD-1 and IL-2." (PMID 39664443, 2024). "Targeting IL-2 to the tumor microenvironment by generating antibody-cytokine fusion proteins (immunocytokine) would be a promising approach to increase efficacy without associated toxicity." (PMID 38337114, 2024). "These TILs are isolated from a growing tumor that has been removed, grown to a large number in the lab using the T cell growth factor interleukin-2 (IL-2), and then reinfused into the same patient under specific conditions to target tumor cells." (PMID 39712007, 2024). "This is exemplified by the known synergy of IL-2 and IL-12 in enhancing T cell and NK cell responses and anti-tumor immunity through mechanisms which include mutual receptor-upregulation." (PMID 39252938, 2024). "The higher motility of IL7/15 CD8+ T cells compared to IL2 cells was also confirmed in tumor slices derived from the BxPC3-NSG model." (PMID 38467616, 2024). "Interleukin-2 (IL-2) is a cytokine produced by T cells that promotes the expansion of cytotoxic T cells, which are essential for targeting and eliminating tumor cells." (PMID 39407789, 2024). "The upregulation of these molecules facilitates the recruitment of anti-tumor T-cells and triggers an immune response accompanied by the release of pro-inflammatory molecules like IL-1, IL-2, IL-6, IL-8, IL-12, VEGF, EGFR, IFN-α, IFN-ß and TNF-α." (PMID 39518094, 2024). "IL-2 promotes the activation and expansion of effector T cells and NK cells, driving anti-tumor immunity." (PMID 39872527, 2024). "In contrast to M5A‐IL‐2, IL‐2‐Fc shows less toxicity in two tumor mouse models and elicits its antitumor effects primarily through Treg depletion." (PMID 38317590, 2024). "For instance, Tregs can convert to Th1 or Th17 types, while Th1 cells secrete cytokines like IFN-γ and IL-2 that enhance anti-tumor immunity, and Th2 cells release IL-4 and IL-10, which can promote tumor growth." (PMID 39769334, 2024). "NK cells can be activated by tumor cells, cytokines [e.g., interleukin (IL)-2, IL-12], natural products (e.g., chitosan) to induce direct lysis of tumor cells through the secretion of toxic molecules [e.g., granzyme B (GZMB) and perforin (PRF1)]." (PMID 39439794, 2024). "Cis-targeting of IL2 to CD8+ T cells shows improved anti-tumor activity and reduced toxicity compared to broadly acting IL2, supporting the evaluation of such a strategy in patients." (PMID 38563906, 2024). "The impact of PF and Sor on tumor growth, proliferation, apoptosis, T-cell subsets, IL-2 and IFN-γ production, and NF-κB and PD-L1 expression was assessed." (PMID 38312647, 2024). "Our study provided compelling evidence of a significant difference in IL-2 secretion only when EGFRvIII-directed CAR-T cells were co-cultured with tumor cells expressing PD-L1." (PMID 39352918, 2024). "Tumor uptake, tissue biodistributions, and PK were compared between IL‐2‐Fc and ICK to determine their relative in vivo fates." (PMID 38317590, 2024). "In a multivariate Cox analysis that considered age, sex, tumor grade, and tumor stage as confounding factors, patients with high expression of IL-2 mRNA had a hazard ratio (HR) for disease mortality of 0.52 (95% CI 0.33–0.81; p = 0.004)." (PMID 38554155, 2024).
tumor (continued). "Cytokines serve as key modulators of the immune environment, and certain pro-inflammatory cytokines possess anti-tumor activity, which has led to the clinical approval of interleukin-2 (IL-2) and interferon-alpha (IFNα) for certain cancer indications." (PMID 38803496, 2024). "High-throughput genetic screening can discern persistence factors by repeatedly stimulating T cells with anti-CD3/CD28 and IL-2 in vitro, or by implanting them into tumor-bearing mice and comparing chronically stimulated T cells with unstimulated counterparts." (PMID 39538305, 2024). "IL2 is also used as a companion therapeutic to enhance the efficacy of adoptive cell therapies such as tumor infiltration lymphocyte therapy." (PMID 38546220, 2024). "IL-2 used directly for improving anti-tumor response of NK cell can trace back to 1985, finding that administrating recombinant IL-2 assisted generation of activated lymphokine killer cells." (PMID 38396050, 2024). "Considering the results from this study, the potential for tachyphylaxis should be considered when designing and evaluating the dosing schedule of other next-generation IL-2 agonists to optimize anti-tumor activity." (PMID 39025948, 2024). "The role of IL-2 as an additional element involved in the attempt to halt the spread of this tumor will also be discussed." (PMID 38893211, 2024). "Treatment of MC38 tumor–bearing mice with exogenous IL-2 and anti–IL-2 complex (clone S4B6-1), which is known to potently expand CD8+ T cells, significantly reduced TOXhi cluster 11 TILs." (PMID 38787791, 2024). "The proposed synergies include, for example, the addition of IL-2 to immune checkpoint inhibitors, such as pembrolizumab, or to adoptive cellular therapy, in particular, Tumor-Infiltrating Lymphocyte (TIL) therapy." (PMID 38893211, 2024). "Activated T-cells (ATCs) combined with bispecific anti-CD3 x anti-Her2/neu antibodies (aATCs) effectively modulate MDSCs via INF and IL-2, suppressing their activity and inhibiting tumor growth." (PMID 38983795, 2024). "While variations exist between each trial, the general strategy involves the expansion of TILs from small, surgically resected tumor samples and, following lymphodepletion, are readministered into the patient, followed by IL-2 treatment." (PMID 38545115, 2024). "Mice were treated with adoptive cell transfer (ACT) three days after tumor engraftment and injection of IL-2 to support transferred cells." (PMID 38745250, 2024). "We also analyzed the immune contexture in different IL2 mRNA expression status and noticed that higher IL-2 mRNA relates to increased proportion of tumor infiltrating lymphocytes (TILs), especially CD8 + T cells, naïve B cells and NK cells." (PMID 38554155, 2024). "Interaction with peptides presented by MHC I on tumor cells induces CD8 T cells to produce cytolytic factors, granzyme and perforin, and cytokines IL-12, IL-2 and IFNγ that act to kill tumor cells." (PMID 38474178, 2024). "Upon CTLA-4 activation, T cell activation and IL-2 secretion are diminished, exerting a negative regulatory effect on tumor immunity." (PMID 39290709, 2024). "For example, the use of IL-2, combined with the carrier L19 (L19-IL2) to enhance tumour specific penetration, has been shown to improve survival in mouse models and is currently being studied in a phase II clinical trial." (PMID 39315059, 2024). "The regulation of IL-2 gene expression involves various transcription factors and plays a significant role in modulating immune responses and anti-tumor activity." (PMID 39583964, 2024). "Various approaches to limit systemic IL-2 exposure and selectively deliver IL-2 directly to the tumor are being explored." (PMID 39114660, 2024). "IL-2 plays a dual role, stimulating the proliferation of effector T lymphocytes that can fight the tumor while also being critical for the development and function of Tregs." (PMID 39727942, 2024).
tumor (continued). "Once activated, these effector T-cells are more likely to penetrate the tumor and exhibit direct cytotoxic effects on tumor cells, while also releasing cytokines such as IL-2 and IFN-γ to stimulate an immunogenic tumor microenvironment." (PMID 38410760, 2024). "Partially exhausted CD8+ T cells have been defined as cells that can produce IFN-γ but lack the ability to produce TNF-α and IL-2, a phenotype consistent with tumor-infiltrating CTLA-4hiPD-1hiCD8+ T cells." (PMID 39273452, 2024). "Tumor samples were finely minced into small 2-3 mm pieces using a surgical scalpel and then cultured with IL-2 for 2 to 3 weeks in a 24-well plate." (PMID 38288307, 2024). "Blockade of interleukin 2 (IL-2) triggering of tumor-derived NK-cells are necessary to enhance NK-cell responsiveness in GBM." (PMID 38279111, 2024). "We also found that a cytokine cocktail (IL-2, IL-9 and IL-21) can effectively amplify the anti-tumour effect." (PMID 39215816, 2024). "TILs are expanded from resected tumor tissue ex vivo using IL-2, and once a patient has received lympho-depleting chemotherapy, the TILs are re-infused into the patient, followed by a systemic application of high-dose IL-2." (PMID 38928238, 2024). "Burst analysis identifies 164 keywords with citation bursts, including interleukin-2 (29.76, 1990-2004), autologous tumor (30.16, 1991-1998), and adoptive immunotherapy (28.4, 1991-2009)." (PMID 39835135, 2024). "We also examined the anti-tumor killing activity of CD8 cells after three expansions with IL-2, and MCJ KO OT-I CD8 cells also showed enhanced killing activity compared to the WT OT-I CD8 cells." (PMID 38789421, 2024). "Their results revealed that patients treated with a combination of LAK/IL-2 and LBP showed a higher response rate and more prolonged mean tumor regression than those given LAK/IL-2 alone." (PMID 38541744, 2024). "The greatest tumor delay involved the triple combination of GM-CSF, IL-2 and HSV-TK adenoviruses, which reduced lung metastases and correlated with an increase in lymphocyte infiltration." (PMID 38803496, 2024). "Lycopene has been shown to enhance the impact of PD-1 mAb therapy, resulting in increased tumor cell death, elevated production of anti-tumor cytokines (IL-2, IFNγ), and a higher CD4+/CD8+ ratio in the spleen." (PMID 38426097, 2024). "T-cells engineered with LMP1-specific TCR can recognise and elicit specific cytotoxicity towards LMP1-expressing tumour cells with increased production of IL-2 and IFN-γ." (PMID 39450176, 2024). "This would enable the amplification of IL-2 response and the rescue of tumour-reactive T cells, which are typically in a dysfunctional state and more susceptible to IL-2 deprivation." (PMID 38658764, 2024). "Here, we analyzed the level of anti-tumor inflammatory cytokines such as IL-2, TNF-α and IFN-γ in the B16-F10 cancer-bearing mice after the treatment with photothermal-immunotherapy by FSGG/siGal-9." (PMID 38366083, 2024). "On the other hand, AgNPs-G treatment significantly decreased the levels of IL-2, IL-4, and IL-10 in tumor tissue compared to the control group." (PMID 39126001, 2024). "Strategic modulation of IL2RA expression in TCR-T therapies can significantly enhance treatment efficacy by increasing T-cell sensitivity to IL-2 within the tumor microenvironment." (PMID 39439803, 2024). "Prostaglandin E2 from the tumour microenvironment impairs interleukin-2 sensing by tumour-infiltrating lymphocytes, restricting proliferative response and promoting T cell death via metabolic impairment and ferroptosis." (PMID 38658764, 2024). "The role of neutrophils after immunotherapy is related to tumor heterogeneity and the presence of cytokines that promote neutrophilic response, especially IL-2, IFN-γ." (PMID 39132507, 2024).
tumor (continued). "First, Tregs promoted CD8+ T cell exhaustion in the tumor by being the main consumer of IL-2; restoration of IL-2 levels locally by blocking gp96/LFA-1–dependent tumor infiltration of Treg was able to reverse CD8+ T cell exhaustion." (PMID 38787791, 2024). "These ADC or IDC can activate and drive unspecifically IL2-responding killer effector cell populations to the tumor." (PMID 38786084, 2024). "Together, these studies support a model wherein delivery of IL-2 to tumor-specific CD8+ T cells is required to achieve optimal IL-2 induced effector T cell responses." (PMID 39114660, 2024). "The ability of IL-2 to mediate tumor regression led to FDA approval for its use in the treatment of metastatic renal cell carcinoma and metastatic melanoma in the 1990s." (PMID 38545547, 2024). "We observed increased Ki67 and decreased PD-1 and TOX expression levels selectively in MART-1-specific COXi TIL, indicating that rescue from PGE2 suppression enhanced response to IL-2 selectively in tumour-reactive TILs." (PMID 38658764, 2024). "It is, therefore, possible that the effect of CXCL10-Fc on NK cells is indirect and is in response to the high levels of IFN-γ, IL-2, and other cytokines at the tumor site." (PMID 39474427, 2024). "In multiple myeloma, IL-2 has the potential to dissolve tumor cells and enhance the killing activity of CD16+ NK cells by promoting the perforin effect mechanism of activating NK cells through the NKG2D pathway." (PMID 39221244, 2024). "This was not limited to type 1 cytokines, as IL-2 secretion was similarly affected in T cells cultured with infected tumours." (PMID 39558103, 2024). "PD-L1, generated by tumor cells, restricts the immune response of the host by binding to PD-1 on the surface of T cells, which inhibits the release of cytokines including interleukin 2 (IL2), tumor necrosis factor alpha (TNFα), and interferon gamma (IFN γ)." (PMID 38893691, 2024). "Adenoviruses engineered to express TNF-alpha and IL-2, when coupled with anti-PD-1 therapy, exhibit augmented tumor control through increased CD8+ T cell infiltration and reduced immunosuppressive cell populations." (PMID 38731910, 2024). "In clinical settings, the concurrent administration of IL-2 has shown improvements in the survival, function, and anti-tumor activity of transplanted T cells." (PMID 39114660, 2024). "The patients included in this study receive a single dose of pembro (after tumor resection and prior to lymphodepletion) as well as adjuvant IL-2." (PMID 39684307, 2024). "successfully inhibited tumor progression and prolonged survival in dogs using autologous cancer cell inoculation, passaged T-cell therapy, and injected interleukin-2 in a canine osteosarcoma model." (PMID 39916962, 2024). "Despite its limitations as monotherapy, systemic IL-2 plays an important role in driving the growth and survival of adoptively transferred tumor-infiltrating lymphocytes (TILs)." (PMID 38928238, 2024). "Endogenous T cells are more readily accessible and require lower doses of interleukin (IL)-2, are not limited to the tumor site, and present less exhaustion and less cytotoxicity." (PMID 38256268, 2024). "The activation of LAK cells involved in the fight against tumor growth thus represents an indirect action that IL-2 manifests on malignant cells." (PMID 38893211, 2024). "Adoptive cell therapy (ACT) involves the extraction of precursor cells from autologous or allogeneic anti-tumor effector cells, followed by their in vitro induction, activation, and expansion using activators such as IL-2 and specific peptides." (PMID 39290709, 2024). "Although high doses of IL-2 show significant anti-tumor efficacy, careful administration is required due to potential toxicities and the expansion of Tregs." (PMID 38891056, 2024). "Nonetheless, through optimizing dosage and treatment protocols, it is possible to maximize the anti-tumor effects of IL-2 while minimizing its potential side effects." (PMID 39267764, 2024).
tumor (continued). "Compared to IL-2-treated mice, P-IL-2-treated mice exhibited slowed tumor growth, as well as a relative decrease in regulatory T cells and a relative increase in CD8+ T cells in the immune microenvironment." (PMID 38352877, 2024). "It involves the extraction of lymphocytes directly from a patient's tumor and their expansion ex vivo in a culture enriched with IL-2, anti-CD3 monoclonal antibodies, and allogeneic feeder cells before their eventual re-infusion for treatment purposes." (PMID 39397869, 2024). "The anti-tumor activity of IL-2 is generally accepted to be mediated by tumor-specific CD8+ T cells." (PMID 39114660, 2024). "Other studies have also shown that intrapleural injection of IL-2 induces anti-tumour activity in patients with MPM." (PMID 38475858, 2024). "Evidence suggests that dysregulated IL-2/IL-2R signaling within the TME can profoundly impact tumor growth and anti-tumor immune responses." (PMID 37516849, 2023). "IL-2 administration was shown to improve tumor ITs by improving tumor-specific T-cell-mediated cellular response." (PMID 37515069, 2023). "We investigated the expression of IFN-γ, IL-2, IL-4 and IL-12 inflammatory cytokines by q-PCR within the tumor tissues." (PMID 37894298, 2023). "In humans, immunotherapy with IL‐2,40, 41 IL‐4,42 granulocyte‐macrophage colony‐stimulating factor, or tumor vaccines often results in peripheral blood eosinophilia." (PMID 37669914, 2023). "This novel immunotherapy approach uses TILs isolated from the patient's tumor and expanded ex vivo using recombinant IL-2 (rIL-2)." (PMID 36810079, 2023). "IL-2 is also able to improve the tumor-killing capacity of different immune system cells by increasing the cytolytic activity of NK cells and lymphokine-activated killer cells and inducing the rapid proliferation of CD8+ T cells." (PMID 36839658, 2023). "We next determined the effects of combined IL12-MSA and IL2-MSA administration compared with either single treatment on the tumor-reactive T cell response in the context of KP.SIY lung tumors." (PMID 37669107, 2023). "IL-2 loaded polymersomes when injected into tumor bearing BALB/c mice have resulted in significant tumor volume reduction from 3600 mm3 to 1200 mm3 within 16 days which indicates their site-specificity and therapeutic efficacy." (PMID 37342386, 2023). "Taken together, these results suggest that MARCH5 knockdown sensitizes the anti-tumor effects of IL-2 as well as its combination with PD-1 blocking antibody." (PMID 37932447, 2023). "In the first in vivo experiment, tumour growth was monitored to determine the growth delay of tumours treated with the individual plasmids IL-2 and IL-12 alone and in combination." (PMID 37629081, 2023). "Emerging IL-2-based therapies show promise in enhancing the anti-tumor immune response and improving the efficacy of immunotherapy in cancer patients." (PMID 37516849, 2023). "IL-2 is a critical cytokine required for T cell survival and activation as well as for increasing infection and tumor immune responses." (PMID 37250453, 2023). "This induces the activation of CD4+ and CD8+ T-cells, which influences cytokine expression (TNF-α, IFN-γ, IL-2) and stimulates tumor cell killing." (PMID 38035338, 2023). "These T cells are unresponsive to subsequent activating conditions with limited IL-2 expression that induce tolerance in the periphery and cell cycle arrest at the G1/S phase, and promote the development of neoplastic diseases." (PMID 36980527, 2023). "CD4+ T cells can promote tumor regression through various mechanisms, including cytokine secretion (IL-2), enhancing tumor-specific CD8+ T-cell function, or directly eliminating cancer cells." (PMID 37638022, 2023). "Upon analysis, we found that the tumor size and weight in the IL-2 alone group were significantly reduced compared to the control group, indicating the efficacy of IL-2 in tumor suppression." (PMID 37711172, 2023).